SIMALR (suppressor of inflammatory macrophage apoptosis lncRNA)
Synonyms: formerly LINC02528
Gene: Long non-coding RNA gene on chromosome 6 (137,941,029 to 137,957,702, reverse strand). Ensembl gene ENSG00000226004.
Diseases named in the same sentence as SIMALR in open-access papers:
SIMALR is named in the same sentence as 2 diseases in open-access papers, as found by Europe PMC text mining. Sharing a sentence is not in itself a finding about the gene and the disease. The quoted sentences say what the papers report.
diabetes (1 paper, 2024). "Therefore, SIMALR could be a promising target in targeting diabetes-affected MΦs." (PMID 39049097, 2024).
SIMALR also shares sentences with these, for which no sentence is quoted: infection (1 paper).